HIF1A (hypoxia inducible factor 1 subunit alpha)
Diseases named in the same sentence as HIF1A in open-access papers (continued):
Sharing a sentence is not in itself a finding about the gene and the disease.
ovarian carcinoma (continued). "Other authors described HIF1A elevated expression in stage III and IV ovarian cancer compared to controls." (PMID 36230822, 2022). "We found that TRPM7 silencing enhanced OXPHOX, inhibited glucose uptake, glycolysis, lactic acid production and suppressed the proliferation of ovarian cancer cells by enhancing AMPK activation and HIF-1α degradation." (PMID 35101076, 2022). "In the field of ovarian cancer, activation of PPAR-α has been involved with suppression of the hypoxia-inducible factor 1 alpha (HIF-1a), a process that was confirmed following the use of proteasome inhibitors, which reversed this process." (PMID 35371629, 2022). "Next, we explored how TRPM7 silencing modulated AMPK activation, HIF-1α expression, OXPHOS and glycolysis in ovarian cancer cells." (PMID 35101076, 2022). "This study investigated the impacts of TRPM7 silencing on ovarian cancer cell proliferation, glucose metabolism and the AMPK / HIF-1α signaling." (PMID 35101076, 2022). "To understand how HIF-1α and AMPK activation regulate the TRPM7 silencing-induced metabolic reprogramming in ovarian cancer cells, we first generated HIF-1α over-expression in TRPM7 silencing ovarian cancer cells." (PMID 35101076, 2022). "Thus, the high level of HIF-1α may be taken as a prognostic marker in ovarian cancer." (PMID 35464826, 2022). "To understand how TRPM7 silencing modulates the HIF-1α and AMPK signaling, we characterized the levels of HIF-1α and AMPK expression and activation in the indicated ovarian cancer cells by Western blot and IHC." (PMID 35101076, 2022). "Within these pathways are factors HIF-1α, IGFBPs, GLUT1, FASN, and leptin, which have all been demonstrated to be potential therapeutic targets in ovarian cancer." (PMID 36230617, 2022). "The shifting from glycolysis to OXPHOS by TRPM7 silencing was abrogated by HIF-1α over-expression and impaired by inhibiting AMPK activity in ovarian cancer cells." (PMID 35101076, 2022). "By using an inhibitor of Src in ovarian cancer cell lines (SKOV-3 and PA-1), norepinephrine-induced HIF-1α, c-Myc expression was inhibited leading to reduced hTERT expression." (PMID 35974340, 2022). "Dynamin2 is a GTPase required for clathrin-mediated endocytosis whose promoter has HIF-binding sites that are reduced in epithelial ovarian cancer cells under hypoxia by HIF-1α and can reciprocally regulate HIF-1α via an iron-dependent mechanism." (PMID 35039054, 2022). "The impacts of TRPM7 silencing on the levels of glycolysis-related HK2, PDK1 and oxidative phosphorylation (OXPHOS)-related IDH3B and UQCRC1, HIF-1α expression and AMPK phosphorylation were determined in ovarian cancer." (PMID 35101076, 2022). "Apparently, the HIF-1α and AMPK signaling has opposite roles in regulating glycolysis and OXPHOS in ovarian cancer." (PMID 35101076, 2022). "It has been shown that ovarian carcinoma cells presented higher VEGFA protein content, and HIF1A level was significantly correlated with VEGFA." (PMID 36230822, 2022). "TCEB2 plays an essential role in the development of acquired resistance to anti-angiogenic therapy in ovarian cancer cells via suppressing VEGF-A expression and promoting HIF-1α degradation." (PMID 34555052, 2021). "miR-138 inhibits the occurrence and development of ovarian cancer by downregulating the expression of SOX12 gene and invasion via SOX4 and HIF-1α oncogenic transcriptional factors." (PMID 33673181, 2021). "HIF-1α also upregulates the expression of Sirtuin type 1, which is known to promote CSC-like features in ovarian cancer cells." (PMID 34867818, 2021). "Real time PCR results from previous studies suggest that taxifolin downregulated the expression of Hif1-α and VEGF in ovarian cancer cells OVCAR-3 and Akt in osteosarcoma U2OS cells." (PMID 34113483, 2021). "Taken together, we identified a new HIF-1α/NOX4 signal pathway which induced drug and radiation resistance in ovarian cancer." (PMID 34209278, 2021).
ovarian carcinoma (continued). "Molecular investigations indicated that MIR210HG directly targets HIF-1α protein and inhibits VHL-dependent HIF-1α protein degradation in ovarian cancer." (PMID 34900667, 2021). "Isoflurane enhanced cell proliferation and migration via hypoxia inducible factor-1α (HIF-1α) and matrix metalloproteinase 9 (MMP9) in prostate and ovarian cancer cells." (PMID 33673181, 2021). "They found that as a downstream target gene of HIF-1α, SIRT1 was involved in the promotion of cancer stem cell-like features in ovarian cancer cells by hypoxia." (PMID 33435147, 2021). "sMEK1 inhibits ovarian cancer cell growth and migration via suppressing VEGFR-2-mediated Akt/eNOS/HIF-1α pathway." (PMID 34977016, 2021). "Previous research showed that Gankyrin regulated HIF-1α protein stability via Akt activation by inhibiting PTEN in the Hey, HO8910 and ES2 ovarian cancer cell lines." (PMID 33802884, 2021). "HIF-1α has also been found to directly induce expression of the STC1 gene, producing STC in human ovarian cancer cell lines." (PMID 34867818, 2021). "The present study with an ovarian cancer cell line (SKOV3) demonstrated that inhalational anaesthetic agents exert procancer effects via miR-138 and/or miR-210/HIF-1α modulations." (PMID 33673181, 2021). "Knockdown of HVEM significantly reduced hypoxia-induced expression of HIF-1α in hypoxic OVCAR3 cells and primary ovarian cancer cells." (PMID 32312328, 2020). "For instance, miR-138 represses ovarian carcinoma cell metastasis via modulating the expressions of SRY-Box Transcription Factor 4 (SOX4) and Hypoxia Inducible Factor 1 Subunit Alpha (HIF-1α)." (PMID 32782028, 2020). "In this work, we investigated the role of HVEM in hypoxic ovarian cancer cells and the relationship between HVEM and HIF-1α by overexpressing and silencing HVEM." (PMID 32312328, 2020). "Overexpression of HVEM markedly enhanced hypoxia-induced expression of HIF-1α in hypoxic OVCAR3 cells and primary ovarian cancer cells further." (PMID 32312328, 2020). "In the previous discussion of ovarian cancer, we mentioned that the effect of LPAR on the transcription factor hypoxia-inducible factor-1α (HIF-1α) is a factor in the development of ovarian cancer." (PMID 32284748, 2020). "Some literatures manifested that SIK2 acted as the oncogene and the crucial regulator of glucose metabolism in ovarian cancer cells through PI3K/AKT/HIF-1α pathway, and SIK2 acted as a critical regulator of lipid synthesis and promotes ovarian cancer growth." (PMID 33344445, 2020). "As GHET1 regulated the expression of HIF1α, we further detected the effect of GHET1 on the glycolysis of ovarian cancer cells." (PMID 30988076, 2019). "Mechanistically, GHET1 interacted with VHL, the E3 ubiquitin ligase of HIF1α, which blocked the binding between VHL and HIF1α in ovarian cancer cells." (PMID 30988076, 2019). "In our previous studies, OCCCs showed the highest frequency of HIF-1α, histone deacetylase (HDAC) 6, and HDAC7 compared to other ovarian epithelial cancer." (PMID 30678691, 2019). "HIF-1α and vascular endothelial growth factor (VEGF) are upregulated by hypoxia-induced LPA signaling in human ovarian cancer cells (OVCAR-3 and CAOV-3)." (PMID 30791624, 2019). "Correlation of HIF-1α, MDR1, and LAPTM4B expression with clinico-pathological features of ovarian cancer." (PMID 30746305, 2019). "Only 25% of ovarian cancer biopsies are positive for VM, which correlates with hypoxia and EMT and is due to the high expression levels of HIF-1α, vimentin, VE-cadherin, Twist1, and Slug." (PMID 31993365, 2019). "Functionally, OPN can promote ovarian cancer growth in cell culture and in vivo by activating the PI3K/AKT/HIF-1α signaling pathway; OPN expression positively correlates with clinical stage, histological grade and lymph node metastasis." (PMID 31035430, 2019). "AEG-1, HIF-1α, and VEGF protein amounts were evaluated by immunohistochemistry in 40 and 170 normal ovary and ovarian cancer tissue specimens, respectively." (PMID 29770329, 2018).
ovarian carcinoma (continued). "We also compared the expression levels of STAT3, SITR3, HIF‐1α, GLUT1, LDHA, and HK2 of 44 ovarian cancer patient serums with 35 normal controls." (PMID 30094960, 2018). "We tested the expression levels of STAT3, SITR3, HIF‐1α, GLUT1, LDHA, and HK2 in 38 ovarian cancer patient tissues and 22 normal tissues." (PMID 30094960, 2018). "Here, we report the transcriptional induction of ETS‐1 upon direct binding to its promoter through HIF‐1α in both HIF‐1α‐overexpressed cells and LPA‐induced ovarian cancer cells." (PMID 28236660, 2017). "Our research demonstrated that high level of HIF-1α and SIRT1 was related to the characteristics of CSCs in ovarian cancer." (PMID 28878214, 2017). "The inhibited angiogenesis effect of TS was correlated with the down-regulation of HIF-1α and VEGF protein levels in ovarian cancer cells." (PMID 28974006, 2017). "It was reported that HIF-1α induced the expression of ADM mRNA under normoxic and hypoxia conditions in the human ovarian carcinoma cell line OVCAR-310, which was opposite to what we observed." (PMID 28091613, 2017). "Dhanasekaran group showed that LPA sensitized the Src/Gαi2 signaling pathway to result in up-regulation of HIF1α and finally initiated EMT phenotype of ovarian cancer cells." (PMID 29029500, 2017). "Here we provided the evidence that HIF-1α and its downstream target gene SIRT1 played an important role in the promotion of CSCs-like properties in ovarian cancer cells." (PMID 28878214, 2017). "Our results suggested that HIF‐1α binds to AEG‐1 promoter to upregulate its expression, which was correlated with metastasis in ovarian cancer by inducing the expression of MMP2 and MMP9 as well as inhibiting expression of E‐cadherin and β‐catenin." (PMID 28401704, 2017). "Overexpression of HIF‐1α upregulated AEG‐1 expression and enhanced migration of ovarian cancer cells by inducing the expression of MMP2 and MMP9 as well as inhibiting the expression of E‐cadherin and β‐catenin." (PMID 28401704, 2017). "Both miR-125 and miR-199a were shown to inhibit angiogenesis through decreased expression of HIF‐1a (Hypoxia-inducible factor 1-alpha) and VEGF (Vascular Endothelial Growth Factor) in ovarian cancer." (PMID 27775664, 2016). "In ovarian cancer, miR-138 can suppress cell invasion and metastasis by targeting SRY-box 4 (SOX4) and hypoxia inducible factor 1, alpha subunit (HIF-1α)." (PMID 27095063, 2016). "Similar effects on cisplatin resistance in vitro and intraperitoneal tumourigenesis in vivo were obtained after HIF1b knockdown in the ovarian cancer cell line SKOV3, which expresses endogenous Rab25 and HIF-1α at atmospheric oxygen concentrations." (PMID 26967059, 2016). "Several studies reveal a connection between the HIF1A/VEGFA axis in drug resistance and poor prognosis in various cancer types including ovarian carcinoma." (PMID 27090655, 2016). "Similar to that seen in ECC-1 cells, TM treatment (30 μM, 24 h) under normoxia effectively reduced the levels of HIF-1α in IGROV-1 and 2008 human ovarian cancer cells, suggesting that the effects of TM on levels of HIF-1α are not cell-specific events." (PMID 26469226, 2015). "We observed that nobiletin inhibits secretion of the key angiogenesis mediators, Akt, HIF-1α, NF-κB and vascular epithelial growth factor (VEGF) by ovarian cancer cells." (PMID 25845666, 2015). "In this study, we mimicked a hypoxic model of ovarian cancer with CoCl2, investigated the effects of SENP1 on HIF-1α and the internal mechanisms, and detected the effects of SENP1 on ovarian cancer chemosensitivity." (PMID 26548925, 2015). "The anti-angiogenic activity of nobiletin was correlated with decreased levels of Akt, HIF-1α, NF-κB and vascular epithelial growth factor (VEGF) in ovarian cancer cells." (PMID 25845666, 2015). "In this study, we demonstrate the level of pSTAT3 Tyr705 is increased in the hypoxic regions of human epithelial ovarian cancer (EOC) specimens, as determined by HIF-1α and CD-31 staining." (PMID 25594014, 2014).
ovarian carcinoma (continued). "Recent studies also suggest that P70S6 kinase, downstream of mTOR, drives the expression of HIF-1α and VEGF in human ovarian cancer, mediating tumor growth and angiogenesis." (PMID 24722367, 2014). "Nox4 knockdown in ovarian cancer cells decreased the levels of VEGF and HIF-1A and tumor angiogenesis." (PMID 24868315, 2014). "Elevated HIF-1α and VEGF levels positively correlated with poor prognosis in ovarian cancer patients." (PMID 23819061, 2013). "HIF-1α and LOX were knocked down in epithelial ovarian cancer cells (EOC), and HIF-1α/LOX regulation mechanism and LOX catalytic activity under hypoxia/reoxygenation microenvironment were explored." (PMID 23545606, 2013). "In conclusion, our study demonstrates that hypoxia-HIF-1α-LOX-AKT pathway regulates the invasion and migration of ovarian cancer cells under hypoxic/reoxygenation microenvironments." (PMID 23545606, 2013). "We found that HIF-1α and LOX are highly expressed in epithelial ovarian cancer tissues, and the expression of both proteins is significantly correlated with the tumor grade, tumor diameter and lymph node metastasis." (PMID 23545606, 2013). "Moreover, Twist2 may be involved in the HIF-1α signaling pathway in ovarian cancer." (PMID 23946798, 2013). "The impact of redox balance fluctuation on HIF-1α expression and stability is well defined, thus we examined HIF-1α protein expression in our ovarian cancer model following GSH depletion." (PMID 24238102, 2013). "IL-6 also activated HIF-1α, which clearly indicates that HIF-1α perhaps is regulated through STAT3 in ovarian cancer cells." (PMID 22280969, 2012). "The effect of hypoxia on the HIF-1α and HIF-2α expressions was investigated in the ovarian cancer cell lines." (PMID 22642602, 2012). "Osada in a recent IHC study (24 patients with ovarian carcinoma stage III/IV patients, 10 of them poorly differentiated G3, followed by cisplatin-based chemotherapy) showed that nuclear HIF1a immunoreactivity was an independent marker of poor prognosis." (PMID 19014607, 2008). "This review provides an analysis of HIF-1α’s role in ovarian cancer progression and its negative impact on female fertility." (PMID 40136686, 2025). "Although our digital twin model predicts a strong anti-angiogenic effect of CAPE in ovarian cancer, available experimental data directly linking CAPE with modulation of the HIF-1α/VEGF-A axis in ovarian cancer remain lacking." (PMID 41463127, 2025). "A study focused on ovarian cancer found that myricetin inhibited the secretion of the angiogenesis mediator vascular endothelial growth factor (VEGF) and reduced the levels of p-Akt and hypoxia-inducible factor-1α (HIF-1α) proteins in ovarian cancer cells." (PMID 40362425, 2025). "We therefore propose that future experimental work is needed (e.g., treatment of ovarian cancer cell lines and endothelial co-cultures under hypoxia) to test whether CAPE indeed suppresses HIF-1α stabilisation and VEGF-A production in ovarian cancer." (PMID 41463127, 2025). "Crucially, we found no studies assessing the effect of CAPE on HIF-1α or VEGF expression or signalling in ovarian cancer cell lines or tumour models." (PMID 41463127, 2025). "HIF1A was also observed to be downregulated, and VEGF upregulated in malignant ovarian tumors." (PMID 40362695, 2025). "IL-6 may facilitate ovarian cancer progression through additional pathways, such as IL-6/JAK2/STAT3, IL-6/STAT3/HIF-1α, and mtDNA/toll-like receptor (TLR9)/NF-κB/IL-6." (PMID 39061859, 2024). "Interestingly, ovarian cancer resistant cells that were originally insensitive to DDP and ATRA showed significantly reduced activity when HIF1α expression was downregulated and treated with DDP in combination with ATRA." (PMID 38195606, 2024). "Importantly, ovarian cancer patients with high expression of both CRABP2 and HIF1α in tumor tissues had the worst prognosis." (PMID 38195606, 2024).
ovarian carcinoma (continued). "Immunofluorescence results in ovarian cancer cells showed that HIF1α was more prominently localized in the nucleus of resistant cells, and knocking down the expression of CRABP2 significantly reduced the level of nuclear HIF1α." (PMID 38195606, 2024). "Looking at these studies, we can conclude that the high levels of NQO1 in ovarian cancer cells play a key role in stabilizing HIF-1α under hypoxia, an important factor characterizing tumor microenvironment, favoring HIF-1α-mediated processes such as tumor angiogenesis and cancer cell proliferation." (PMID 37175546, 2023). "The relationship between CoCl2 exposure (HIF-1α inducer) and the expression of vimentin, epithelial cell adhesion molecule (EpCAM), and the growth factor receptor (HER2) was examined in ovarian cancer cells." (PMID 36879003, 2023). "HIF-1α upregulation of WTAP expression interferes with miRNA processing and accelerates the Warburg effect (glucose metabolism by regulating glycolytic enzymes) in ovarian cancer in an m6A-dependent manner." (PMID 37194218, 2023). "Moreover, RES was shown to effectively block lysophosphatidic acid (LPA)-induced hypoxia-inducible factor 1-alpha (HIF-1α) and vascular endothelial growth factor (VEGF) expression in OVCAR-3 and CAOV-3 ovarian cancer cells." (PMID 37242538, 2023). "Moreover, treatment with CC also decreased the ubiquitination of HIF-1α in both control and TRPM7 silencing ovarian cancer cells under hypoxic and normoxic conditions." (PMID 35101076, 2022). "Furthermore, HIF-1α induces autophagy and is critical for the maintenance of cancer stem cell (CSC) populations in ovarian cancer." (PMID 35326569, 2022). "Nevertheless, data regarding HIF1A, EPAS1, and VEGFA expression in ovarian cancer are scant." (PMID 36230822, 2022). "Hypoxia induces a significant increase in both HIF-1α and VEGF in ovarian cancer." (PMID 36230617, 2022). "Furthermore, treatment with CC to inhibit AMPK activation restored HIF-1α protein levels in both control and TRPM7 silencing ovarian cancer cells under hypoxic and normoxic conditions." (PMID 35101076, 2022). "Additionally, the activation of HIF1A and EPAS1 in cancer is connected with the vascularization processes, and ovarian carcinoma cells have been shown to express elevated VEGFA levels." (PMID 36230822, 2022). "Furthermore, HIF-1a induced MMP13 expression appears to promote invasion and metastasis in ovarian cancer as well." (PMID 35311102, 2022). "It is possible that TRPM7 silencing may activate the AMPK to promote HIF-1α ubiquitination proteasomal degradation that attenuates the HIF-1α-enhanced glycolysis to shift glycolysis to OXPHOS, inhibiting the proliferation of ovarian cancer cells." (PMID 35101076, 2022). "Galangin has been previously investigated in numerous studies and has exhibited anti-angiogenic and metastatic potential in liver cancer (HepG2) and ovarian cancer (OVCAR-3) cells, via suppression of the PKC/ERK and Akt/p70S6K/HIF-1α signaling pathways, respectively." (PMID 35479311, 2022). "Moreover, hypoxia treatment augmented the responsiveness of ovarian cancer cells to LPS, including the TLR4 expression level and the downstream NF-κB and HIF-1α activities." (PMID 35464826, 2022). "In ovarian cancer, SIK2 upregulates HIF-1α, which then increases glycolytic enzyme HK2 translation." (PMID 36230617, 2022). "Therefore, TRPM7 silencing enhanced AMPK activation to promote the ubiquitination and proteasomal degradation of HIF-1α, shifting glycolysis to OXPHOX in ovarian cancer cells." (PMID 35101076, 2022). "In addition, this biolipid induces HIF-1α expression to increase VEGF expression and ovarian cancer progression." (PMID 34065317, 2021).